TCEAL7 (transcription elongation factor A like 7)
Description:
Plays a role in the negative regulation of NF-kappa-B signaling at the basal level by modulating transcriptional activity of NF-kappa-B on its target gene promoters. Associates with cyclin D1 promoter containing Myc E-box sequence and transcriptionally represses cyclin D1 expression. Regulates telomerase reverse transcriptase expression and telomerase activity in both ALT (alternative lengthening of telomeres)and telomerase-positive cell lines.
Synonyms: MGC23947; WEX5
Tractability: No criterion of Open Targets' tractability assessment is met for any kind of drug.
Gene: Protein-coding gene on chromosome X (103,330,178 to 103,332,326, forward strand). Ensembl gene ENSG00000182916.
Subcellular location: Nucleus
Subcellular location (Human Protein Atlas): Nucleoplasm
Gene Ontology:
Biological process: negative regulation of DNA-templated transcription
Cellular component: nucleoplasm; nucleus
Homologues: Orthologues: chimpanzee TCEAL7 (100% identical), macaque TCEAL7 (99% identical), rabbit TCEAL7 (95% identical), pig TCEAL7 (92% identical), rat Tceal7 (79% identical), mouse Tceal7 (74% identical). Paralogues in human: TCEAL8 (44% identical), TCEAL9 (43% identical), TCEAL1 (38% identical), TCEAL3 (32% identical), TCEAL5 (32% identical), TCEAL6 (31% identical), TCEAL4 (29% identical), TCEAL2 (28% identical).
Diseases named in the same sentence as TCEAL7 in open-access papers:
TCEAL7 is named in the same sentence as 20 diseases in open-access papers, as found by Europe PMC text mining. Sharing a sentence is not in itself a finding about the gene and the disease. The quoted sentences say what the papers report.
glioblastoma (7 papers, 2020 to 2023). The most malignant astrocytic tumor (WHO grade IV). "An additional report has also demonstrated that TCEAL7 interacts with β-catenin and prevents its nuclear translocation, thereby obstructing Wnt/β-catenin signaling in glioblastoma." (PMID 37047236, 2023). "The revealed exo-miR-301a/TCEAL7-signaling axis has been suggested as a potential target for the sensitization of glioblastoma multiforme to radiotherapy." (PMID 33806538, 2021). "Thus, exo-miR-301a/TCEAL7-signaling axis would most likely provide new ideas for overcoming radioresistance in glioblastoma patients." (PMID 35484557, 2022). "Exosomal miR-301a is secreted by hypoxic glioblastoma (GBM) cells and targets transcription elongation factor A like 7 (TCEAL7), which, in turn, results in the activation of the Wnt/β-catenin signaling pathway." (PMID 32252322, 2020).
ovarian carcinoma (7 papers, 2013 to 2023). A malignant neoplasm originating from the surface ovarian epithelium. "Among the hypermethylated and downregulated genes, TCEAL7 is a putative tumor suppressor gene downregulated by DNA methylation in ovarian cancer." (PMID 34298834, 2021). "WBP5 (pp21 homolog) is homologous to TCEAL7, which is regarded as a possible tumor suppressor gene in ovarian cancer." (PMID 31828091, 2019). "Downregulation of Bex4 (also known as Transcription Elongation Factor S-II Protein-Like 7, TCEAL7) results in increased NF-κB activity in ovarian cancer cells." (PMID 25612294, 2015). "Early studies have shown that human TCEAL7 can inhibit Cyclin D1 expression induced by c-Myc in ovarian epithelial cells and negatively regulate NF-κB signaling through repressing p65 transcriptional activity in ovarian cancer cells." (PMID 37047236, 2023). "In addition, previous studies found that TCEAL7 was downregulated in various human tumors including ovarian cancer, but its specific roles in tumors have been rarely reported." (PMID 34853307, 2021).
breast carcinoma (4 papers, 2021 to 2025). "A recent report has revealed that TCEAL7 regulates epithelial-mesenchymal transition, invasion and metastasis of breast cancer through the NF-κB pathway." (PMID 37047236, 2023). "In this study, we found that TCEAL7 is negatively regulated by miR-18b, in vivo, and in vitro experiments have demonstrated that exosomal miR-18b can promote the migration and invasion of breast cancer cells by targeting the expression of TCEAL7." (PMID 34853307, 2021). "Here, our data verified that TCEAL7 was negatively correlated with the expression of miR-18b in breast cancer tissues and was identified as the direct target gene of miR-18b in breast tumor cell lines." (PMID 34853307, 2021). "Consistently, our results revealed the role of NF-κB in the downstream pathway of miR-18b-TCEAL7 axis in breast cancer by demonstrating that TCEAL7 can inhibit NF-κB activation, thereby stabilizing Snail and ultimately inhibiting EMT." (PMID 34853307, 2021). "The initial finding of our bioinformatics analysis was that TCEAL7 is poorly expressed in breast cancer." (PMID 34853307, 2021). "Rescue experiments illustrated that TCEAL7 was able to abolish the regulatory effects of miR-18b on the invasion and migratory abilities of breast cancer cells." (PMID 34853307, 2021). "Further study suggests that CAFs-derived metastatic exosomes miR-18b could activate NF-κB pathway by downregulating TCEAL7 expression in breast cancer cells to promote the malignant progression of tumors." (PMID 34853307, 2021). "Together, these in vitro data indicate that TCEAL7 could reverse EMT by suppressing NF-κB pathway to suppress breast cancer cell invasion and metastasis." (PMID 34853307, 2021). "In addition, our study unraveled that TCEAL7 was the target gene of miR-18b, the expression of TCEAL7 in breast cancer tissues was lower than that in normal tissues and negatively correlated with pathological grade." (PMID 34853307, 2021). "In addition, Kaplan-Meier analysis on breast cancer patients stratified by TCEAL7 mRNA levels showed that low TCEAL7 mRNA level (probe 227705_at) is correlated with lower overall survivals than patients with high TCEAL7 mRNA levels." (PMID 34853307, 2021). "As major component of breast cancer TME, CAFs-derived exosomal miR-18b promotes breast cancer invasion and metastasis by regulating TCEAL7." (PMID 41029829, 2025). "Overall, our findings suggest that CAFs-derived exosomes miR-18b promote nuclear Snail ectopic by targeting TCEAL7 to activate the NF-κB pathway, thereby inducing EMT, invasion, and metastasis of breast cancer." (PMID 34853307, 2021). "Moreover, exosomal miR-18b can promote breast cancer cell invasion and metastasis by specifically targeting 3′UTR of Transcription Elongation Factor A Like 7 (TCEAL7)." (PMID 39684264, 2024). "Furthermore, microRNA (miR)-18b was upregulated in CAFs-derived exosomes, and CAFs-derived exosomes miR-18b can promote breast cancer cell migration and metastasis by specifically binding to the 3′UTR of Transcription Elongation Factor A Like 7 (TCEAL7)." (PMID 34853307, 2021). "However, the detailed role of TCEAL7 has not been thoroughly clarified in breast cancer." (PMID 34853307, 2021).
gastric cancer (3 papers, 2013 to 2022). A primary or metastatic malignant neoplasm involving the stomach. "Multivariate analysis also demonstrated that TCEAL7 expression (P = 0.009), age, tumor size, histological grade, lymphovascular invasion, T stage, N stage and M stage were independent risk factors in the prognosis of gastric cancer patients." (PMID 23372750, 2013). "Relationship between TCEAL7 expression (localized to the nucleus) and clinicopathologic features of patients with gastric cancer." (PMID 23372750, 2013). "We sought to investigate the expression levels and prognosis value of TCEAL7 in primary gastric cancer." (PMID 23372750, 2013). "The TCEAL7 expression level was significantly lower in the gastric cancer cell lines comparing with the levels of TCEAL1, TCEAL3, TCEAL4, TCEAL5 and TCEAL8." (PMID 23372750, 2013). "Among the 406 gastric cancer samples, 230 (56.7%) showed high TCEAL7 expression (TCEAL7 ++ or TCEAL7 +++), whereas the remaining 176 cases (43.3%) displayed low TCEAL7 expression (TCEAL7− or TCEAL7 +)." (PMID 23372750, 2013). "In order to confirm the molecular biological findings and investigate the clinicopathological the prognostic roles of TCEAL7 expression, we performed immunohistochemical analysis in 406 paraffin-embedded gastric cancer sections." (PMID 23372750, 2013). "We also found that gastric cancer patients with low expression of TCEAL7 showed shorter postsurgical survival than high TCEAL7 expression patients." (PMID 23372750, 2013). "RT- qPCR data showed that mRNA expression level of TCEAL7 was significantly lower in the gastric cancer cell lines comparing with the levels of other five members of the TCEAL family." (PMID 23372750, 2013). "In this study, we aimed to analyze the TCEAL7 expression level in gastric cancer using real-time quantitative RT-PCR (reverse transcription polymerase chain reaction), western blotting and immunohistochemistry." (PMID 23372750, 2013). "The mechanism involved in the biological function of TCEAL7 in gastric cancer warrants further investigation." (PMID 23372750, 2013). "The TCEAL7 protein levels in the resected gastric cancer samples were determined by Western blotting." (PMID 23372750, 2013). "In this study, we investigated the expression of a proapoptotic nuclear protein, TCEAL7 in gastric cancer." (PMID 23372750, 2013). "Nevertheless, the molecular biological functions of TCEAL7 in the progression, invasion and local metastasis of gastric cancer need to be further investigated." (PMID 23372750, 2013). "We found that the expression of TCEAL7 was significantly reduced at both mRNA and protein levels in gastric cancer compared with normal gastric mucosa." (PMID 23372750, 2013). "However, to the best of our knowledge, no previous reports exist concerning the expression status of TCEAL7 in primary gastric cancer, and the prognostic value of this protein in gastric cancer has not yet been assessed." (PMID 23372750, 2013). "Furthermore, TCEAL7 expression level was significantly lower in the gastric cancer cell lines than in the GES1normal gastricepithelial cell line." (PMID 23372750, 2013). "Furthermore, we identified the relationship between TCEAL7 expression and the clinicopathological features of the disease and evaluated its prognostic value for post-resection survival in gastric cancer." (PMID 23372750, 2013). "Additionally, TCEAL7 expression level was significantly lower in the gastric cancer cell lines than in the GES1normal gastricepithelial cell line, indicating that down-regulated TCEAL7 expression may play a role in gastric cancer development." (PMID 23372750, 2013). "Moreover, we analyzed TCEAL7 expression in 406 gastric cancer patients using immunohistochemistry." (PMID 23372750, 2013).
gastric cancer (continued). "A real-time quantitative PCR was performed on normal gastricepithelial cell line GES1 and gastric cancer cell lines including AGS, MKN45, MGC803, SGC7901 and HGC27 to determine the mRNA levels of TCEAL1, TCEAL3, TCEAL4, TCEAL5, TCEAL7 and TCEAL8." (PMID 23372750, 2013). "We investigated TCEAL7 and other homologous five members of the TCEAL family expression in normal gastricepithelial cell line and gastric cancer cell lines using real-time quantitative PCR." (PMID 23372750, 2013). "The transcriptional levels of TCEAL7 were determined with qRT-PCR assays using 39 pairs of resected specimens (tumor tissue samples and matched adjacent non-tumor tissue samples) from gastric cancer patients." (PMID 23372750, 2013).
glioma (2 papers, 2021). A benign or malignant brain and spinal cord tumor that arises from glial cells (astrocytes, oligodendrocytes, ependymal cells). "One recent study suggested that miR-301a in exosomes secreted by hypoxic glioma cells activated the Wnt/β-catenin signal pathway by targeting TCEAL7 and improved radiotherapy resistance and that TCEAL7 was a confirmed GBM suppressor gene." (PMID 33670924, 2021). "For example, miR-21 is related to various cellular responses regulating radio- and/or chemosensitivity, and miR-301a promotes radiation resistance to glioma cells by downregulating a tumor suppressor gene, transcription elongation factor A-like 7 (TCEAL7)." (PMID 34202078, 2021).
Ductal carcinoma in situ (1 paper, 2021). "Conformably, reduced TCEAL7 mRNA levels were also found in BC samples including invasive breast carcinoma, invasive ductal breast carcinoma, Ductal carcinoma in situ, invasive lobular breast carcinoma as compared with the corresponding normal breast tissues (P < 0.05)." (PMID 34853307, 2021). "B−E Differential expressions of TCEAL7 mRNA in the 10 datasets included in the meta-analysis (Normal: normal adjacent breast tissue; IC: invasive breast carcinoma; IDC: invasive ductal breast carcinoma; DCIS: Ductal carcinoma in situ; ILC: invasive lobular breast carcinoma)." (PMID 34853307, 2021).
endometrial cancer (1 paper, 2023). Primary or metastatic malignant neoplasm involving the endometrium (mucous membrane that lines the endometrial cavity). "It has been shown that as a result of increased expression of miR-182, the expression of the target gene-TCEAL7 (transcription elongation factor A-like 7) was reduced in endometrial cancer, which led to the increased expression of c-Myc, cyclin D1 and activation of NFκB." (PMID 37371799, 2023). "Reducing the expression of the endometrial cancer oncogene miR-182 led to the inhibition of colony formation and cell proliferation as a result of the abolition of the inhibition of the suppressor gene TCEAL7." (PMID 37371799, 2023).
gastric adenocarcinoma (1 paper, 2013). "Kaplan–Meier survival curves revealed that the reduced expression of TCEAL7 was associated with a poor prognosis in gastric adenocarcinoma patients (P<0.001)." (PMID 23372750, 2013). "In conclusion, this is the first report that the low expression of TCEAL7 was associated with gastric adenocarcinoma prognosis." (PMID 23372750, 2013). "Immunohistochemical staining data showed that TCEAL7 expression was significantly decreased in 43.3% of gastric adenocarcinoma cases." (PMID 23372750, 2013). "Moreover, we expect that TCEAL7 may function as a useful target for new therapeutic interventions against gastric adenocarcinoma." (PMID 23372750, 2013).
lung carcinoma (1 paper, 2013). "It was also found that TCEAL7 expression was lost in a range of cancer cells, including ovarian, cervical, breast, brain and lung cancer cell lines." (PMID 23372750, 2013).
renal cell carcinoma (1 paper, 2024). "Interestingly, high expressions of Myo18b, Ckmt2, and Eef1a2 showed unfavorable prognoses in H&N cancer, and Sln (sarcolipin) and Tceal7 are unfavorable for renal cell carcinoma." (PMID 38686626, 2024).
tumor (14 papers, 2013 to 2025). "Downregulation of TCEAL7 is associated with larger tumor size, higher tumor stage, and poor prognosis." (PMID 37511248, 2023). "Tceal7 has been associated with tumor suppression and shown to be negatively regulated by miR-182." (PMID 35216152, 2022). "Furthermore, low expression of TCEAL7 was associated with larger tumor size, higher histological grade and N stage." (PMID 23372750, 2013). "By suppressing the tumor suppressor TCEAL7, exo-miR-301a contributes to therapeutic resistance, positioning the exo-miR-301a/TCEAL7 axis as a key target in GBM treatment." (PMID 39928285, 2025). "Methylation of a CpG site inside the promoter is correlated with negative regulation of TCEAL7 gene in both tumors and tumor cell lines." (PMID 38827026, 2024). "ExomiR-18b is seen to induce tumour invasion and metastasis in mouse models as the overexpression of ExomiR-18b suppresses the expression of transcription elongation factor A-like 7 (TCEAL7)." (PMID 38455764, 2024). "Studies show that TCEAL7 is down-regulated in many tumors, and is considered as a putative tumor suppressor gene." (PMID 37976136, 2023). "TCEAL7 is downregulated in multiple tumors and functions as a tumor suppressor, such as non-small cell lung cancer." (PMID 34853307, 2021). "Exosomal miR-301a directly targeted TCEAL7 genes, which function as tumor suppressors in GBM progression, and actively suppressed their expression in normoxic glioma cells." (PMID 32746854, 2020). "The result also showed that the low TCEAL7 expression was significantly correlated with female, larger tumor size, higher histological grade and worse nodal status." (PMID 23372750, 2013). "Based on this model, age, tumor size, histological grade, lymphovascular invasion, TCEAL7 expression, T stage, N stage and M stage remained independent prognostic factors." (PMID 23372750, 2013). "This recently discovered exo-miR-301a/TCEAL7-signaling axis could be a new target for reversing tumor cell resistance to radiotherapy in GBM patients." (PMID 32746854, 2020). "Our study suggests that TCEAL7 might serve as a candidate tumor suppressor and a potential prognostic biomarker in gastric carcinogenesis." (PMID 23372750, 2013). "We confirmed that TCEAL7 might serve as a candidate tumor suppressor and prognostic biomarker in gastric carcinogenesis." (PMID 23372750, 2013). "One example is the Transcription elongation factor A domain (TF_A/BEX domain), present in a family of transcription factor genes located on chromosome X and which include TCEAL7, a putative tumour suppressor gene, which negatively regulates NF-kappaB mediated pathways." (PMID 23425224, 2013). "The fact that TCEAL7, a death/apoptosis regulating protein, has been found to frequently be inactivated in ovarian malignancies among these data suggests that it may function as a tumor suppressor in this cancer type." (PMID 38827026, 2024). "The TCEAL7 mRNA levels were significantly reduced in 27 (69.2%) tumor tissue samples, compared with its levels in the adjacent non-tumor tissue samples (P = 0.025), whereas there were only 5 (12.8%) noncancerous tissue samples' TCEAL7 expression were lower than matched tumor tissue samples." (PMID 23372750, 2013). "According to a study by Lopez‐Serra and colleagues, MBDs show a high affinity for the in vivo binding of TSGs with hypermethylated promoter CpG islands, and their occupancy profiles vary depending on the gene and type of tumor, methylation inactivated a new candidate TSG TCEAL7 in ovarian cancer." (PMID 38827026, 2024). "Results also revealed decreased TCEAL7 mRNA (P = 0.025) and protein (P = 0.012) expression in tumor tissue samples compared with matched adjacent non-tumor tissue samples." (PMID 23372750, 2013).
cancer (5 papers, 2013 to 2024). A tumor composed of atypical neoplastic, often pleomorphic cells that invade other tissues. "Recently, a number of miRNAs have been reported in cancer progression through targeting human Tceal7, such as miR-182, miR-301a, miR-769–5p, miR-18b and miR-758-3p." (PMID 35336819, 2022). "Then we separated cancer cells from the metastases of mice lung tissues and detected miR-18b, TCEAL7, E-cadherin, and Vimentin expression in lung metastatic cells." (PMID 34853307, 2021). "Experimental data demonstrated that TCEAL7 protein represses cellular transformation by negatively modulating Myc and NF-κB, whereas low expression of TCEAL7 promoted the survival of malignant transformed cells, leading to the development of cancer." (PMID 23372750, 2013). "Up to date, there are few studies about the expression of TCEAL7 in cancer in large sample size." (PMID 23372750, 2013). "Therefore, it is worthy to further investigate in the future whether human TCEAL7 regulates Cdk1 activity in cancer progression through the mechanism revealed in our present work, which may provide a novel strategy for cancer treatment." (PMID 37047236, 2023).
heart diseases (1 paper, 2024). "The examples of Penk, Tceal7 and Ankrd23 highlight factors with some evidence for a function in muscle differentiation or LV heart diseases, which, however, so far have not been investigated for their specific roles in right heart (patho)physiology." (PMID 39196177, 2024).
TCEAL7 also shares sentences with these, for which no sentence is quoted: breast tumor (1 paper); gastric tumor (1); invasive breast carcinoma (1); invasive ductal breast carcinoma (1); invasive lobular breast carcinoma (1); lung diseases (1); prostatic neoplasms (1).